UCP2 (uncoupling protein 2)
Diseases named in the same sentence as UCP2 in open-access papers (continued):
Sharing a sentence is not in itself a finding about the gene and the disease.
Obesity (continued). "This review covers the main Ucp SNPs A–3826G, A–1766G, A–112C, Met229Leu, Ala64Thr (Ucp1), Ala55Val, G–866A (Ucp2), and C–55 T (Ucp3), which may be associated with the development of obesity, disturbance in lipid metabolism, T2D, and cardiovascular diseases." (PMID 32450815, 2020). "It was previously shown that UCP2 gene polymorphism was associated with obesity." (PMID 30719347, 2019). "The hypothesis that UCP2 is at the crossroads of a metabolic switch is supported by the fact that mutations in UCP2 cause hyperinsulinism and that increased UCP2 expression is associated with a reduced risk of obesity and type-2 diabetes in humans." (PMID 31510000, 2019). "Moreover, it has been reported that obesity-related fatty liver is unchanged in mice deficient in mitochondrial UCP2." (PMID 31035507, 2019). "Several studies have found that UCP2 polymorphisms are associated with obesity and hypertension." (PMID 29529994, 2018). "Moreover, the promoter variant (−866G>A) has been associated with obesity and/or type 2 diabetes in several studies, with the A allele having greater UCP2 expression and lower glucose-stimulated insulin secretion (GSIS) than the G allele." (PMID 29351723, 2018). "In proinflammatory M1 macrophages that accumulate in adipose tissue during obesity-linked metabolic diseases, UCP2 expression is blocked by adipocyte FA binding protein (FABP4/aP2), and the resulting release of redox signaling is involved in inflammasome activation and IL-1β secretion." (PMID 29351723, 2018). "Furthermore, few case-control genetic association studies reported significant associations between UCP2 gene polymorphisms and obesity and diabetes in humans." (PMID 29163755, 2017). "Moreover, it has been reported that obesity-related fatty liver is unchanged in UCP2 mitochondrial-deficient mice." (PMID 28696376, 2017). "In a population based study, it was shown that UCP2 gene polymorphism was associated with obesity." (PMID 28686191, 2017). "In this regard, elevated RAS activity in adipocytes may play a particular role 90, raising the prospect that the recognised association between UCP2/3 genotype and obesity/diabetes 41, 42, 45, 46, 49, 91, 92 might be partly adipose‐RAS mediated." (PMID 27347560, 2016). "It has been proposed that carriers of the exon-8 insertion allele in the UCP2 gene may have a greater risk of developing obesity." (PMID 24398006, 2014). "Uncoupling protein 2 gene polymorphisms are associated with obesity in some Asian populations." (PMID 23039238, 2012). "The commonly observed UCP2 gene single nucleotide polymorphisms (SNPs) G(−866)A in the promoter region (rs659366) and Ala55Val (a C to T substitution) in exon 4 (rs660339) have been associated with obesity and T2DM to a certain degree." (PMID 22533685, 2012). "In the obese state, the risk would be increased due to insulin resistance, which may accompany obesity and impairment of glucose-stimulated insulin secretion attributable to UCP2 at-risk genotype." (PMID 22533685, 2012). "The UCP2 gene is located at chromosome 11q13, and many studies have reported the association of the G-866A and A55V polymorphisms of UCP2 with various diseases, such as obesity, diabetes, and metabolic syndromes." (PMID 22927880, 2012). "An increase in UCP2 levels might be expected to increase energy expenditure and decrease the risk of obesity." (PMID 20953398, 2011). "UCP2 was initially identified as the gene linked to obesity and hyperinsulinemia." (PMID 21935467, 2011). "We speculated that bererine could upregulate UCP2, increase energy dissipation, and decrease the risk of obesity." (PMID 20953398, 2011). "Several population studies now show that a common functional polymorphism in the UCP2 promoter (-866G/A, the same polymorphism found to be associated with resistance to obesity in Caucasians) enhances UCP2 transcriptional activity and increases the risk of developing type-2 diabetes." (PMID 16968550, 2006).
Obesity (continued). "UCP2 is a member of inner mitochondrial membrane proteins that plays important roles in regulating fatty acid oxidation, mitochondrial biogenesis, and oxidative stress, and its reduction, which occurs in diabetes and obesity, is associated with increased oxidative stress and cardiac dysfunction." (PMID 38134189, 2023). "However, the association between UCP2 genetic risk factors and obesity was only found in urban." (PMID 31915589, 2020). "However, it is unclear how UCP2 gene polymorphism was associated with obesity." (PMID 30719347, 2019). "However, it is unclear how UCP2 gene polymorphism was associated with obesity in human." (PMID 28686191, 2017). "In addition, in Patient 1, we found a de novo sequence variant in the UCP2 gene, a transporter protein present in the mitochondrial inner membrane that is a key regulator of energy balance, the variants of which have already been associated with obesity." (PMID 25158045, 2014). "Thus, the role of the UCP2 variants as obesity and/or diabetes risk factor might be overshadowed by environmental influence in some populations." (PMID 22533685, 2012). "Interestingly, UCP2, which encodes a mitochondrial transporter, was initially presented as a gene possibly linked to obesity and hyperinsulinism in mice since it maps to regions of human chromosome 11 and mouse chromosome 7 that have been linked to hyperinsulinemia and obesity." (PMID 19065272, 2008). "With aging, this seems to lead to insulin resistance and obesity due to the downregulation of the Sirt1-Pgc1a-Ucp2 axis." (PMID 38891115, 2024). "In contrast, the level of the mitochondrial antioxidant UCP2 was significantly higher in the maternal obesity group compared to the maternal lean group (p = 0.0104)." (PMID 39409195, 2024). "The second prominent characteristic of the obesity-resistant NR phenotype in our study was the upregulation of uncoupling protein 2 (Ucp2)." (PMID 38276304, 2024). "In AP, especially in obesity-associated AP, FABP4 upregulates UCP2, which in turn reduces oxidative stress to modulate macrophage signaling and inflammatory responses." (PMID 39707176, 2024). "When compared to the HFD controls, obesity-resistant NR mice showed the capacity to significantly upregulate mitoferrin 1 (Slc25a37, 4.9-fold) and uncoupling protein 2 (Ucp2, 2.4-fold)." (PMID 38276304, 2024). "In line with obesity and reduced expression of the Sirt1-Pgc1a-Ucp2 axis, we found that Chr4Δ70/Δ70 mice also developed insulin resistance during aging." (PMID 38891115, 2024). "In conclusion, the data presented in the current study suggest that ACOT1 inhibition attenuates BW gain during diet-induced obesity by increasing energy expenditure through UCP2 in hepatocytes." (PMID 37561578, 2023). "A total of 175 genes including thermogenic markers (UCP2, CKMT2, and CITED1) and 5 BATLAS markers (PPARGC1B, ACO2, ACSF2, NNAT, and DMRT2) were expressed less in active beige adipocytes carrying FTO obesity-risk variant as compared to risk-free carriers." (PMID 37416800, 2023). "The polymorphism of UCP-2 gene such as −866G>A (rs659366), Ala55Val (rs660339), −5331G>A, exon 8 deletion/deletion, and 45 bp insertion/deletion in 3′UTR results in obesity, type-2 diabetes, and neural tube defects." (PMID 36900198, 2023). "It has been reported that obesity-induced UCP2 expression in hepatocytes promotes hepatic ATP depletion and causes acute liver injury." (PMID 35624769, 2022). "Their study indicated that the HFD increases UCP2 expression in white adipose tissue in obesity- and diabetes-resistant mouse strains." (PMID 35323702, 2022). "In contrast, increased UCP2 contributes to reducing obesity because UCP2 upregulation augments energy expenditure in adipocytes and skeletal muscle." (PMID 36266633, 2022). "The most studied obesity mouse models, the ob/ob mice, have elevated UCP2 expression and impaired insulin secretion." (PMID 35323702, 2022).
Obesity (continued). "HFD increases the mitochondrial number and the mRNA expression of the uncoupling protein 2 (UCP2); the selective deletion of UCP2 in microglia prevents diet-induced obesity." (PMID 35422689, 2022). "On the other hand, overexpression of UCP2 proteins in mice decreases obesity and improves insulin sensitivity." (PMID 35323702, 2022). "On the other hand, UCP2 overexpression decreases insulin secretion in beta-cells, leading to obesity, β-cell dysfunction, and type 2 diabetes." (PMID 35323702, 2022). "Based on studies, modifying the expression of genes that regulate UCP-2 expression and functions is a promising therapeutic approach for controlling insulin resistance, obesity, and body-weight gain or body mass index (BMI)." (PMID 33957975, 2021). "In aP2-agouti transgenic mice, substantial amounts of calcium minerals can move into fat cells and therein increase FAS expression levels and reduce UCP2 expression levels, resulting in obesity." (PMID 34065270, 2021). "UCP2 is a mitochondrial anion that is upregulated in macrophages and human adipose tissue and has recently gained popularity in the field of obesity research." (PMID 33935708, 2021). "Studies have revealed that upregulation of UCP2 and UCP3 due to increased elevation of free fatty acids and mitochondrial ROS generation, as well as in the case of advanced obesity, caused cell death and heart seizure." (PMID 34828008, 2021). "Hepatocytes up-regulate Ucp2 as an adaptation to obesity, but cells become vulnerable to ATP depletion and these cells are vulnerable to necrosis." (PMID 34684533, 2021). "For example, overexpression of PPARγ through increasing physical activity performance, UCP2 expression, and thereby mitochondrial metabolism decreases fat mass and obesity." (PMID 34458651, 2021). "UCP2 protein has been associated with resting energy expenditure, as subjects with obesity and low level of UCP2 protein have low resting energy expenditure." (PMID 33964966, 2021). "The authors also reported that UCP2 was significantly upregulated in isolated pancreatic islets of a model of obesity-induced diabetic mice (ob/ob mice), when compared to control." (PMID 34829617, 2021). "In an in vivo study (2019), it was reported that obesity induced by an HFD determined early activation of microglia and hypothalamic inflammation with hyper-expression of uncoupling protein 2 (UCP2) mRNA associated with mitochondrial dysfunction." (PMID 32414136, 2020). "Molecular epidemiology studies found UCP2 polymorphism alters the risk of developing CAD in some populations, while the relation between UCPs and obesity was widely recognized in several populations." (PMID 32028915, 2020). "Meanwhile, it was reported that the expenditure of 60% of dietary energy as ω-3 fatty acids improved uncoupling protein 2 in liver and prevented obesity in mice." (PMID 31703286, 2019). "Using two genetic mouse models of obesity, about a fivefold increase in steady-state UCP2 transcript levels relative to lean littermate controls was determined." (PMID 29351723, 2018). "UCP2 was increased by HFD in response to enhanced β-oxidation as resistance to obesity or defense mechanism." (PMID 29558403, 2018). "We demonstrated that in the context of high fat diet (HFD)-induced obesity, Ucp2-/- further impairs nitric oxide-dependent vasodilation, while UCP2 overexpression in vivo rescues obesity-related endothelial dysfunction." (PMID 30116205, 2018). "Obesity and T2DM closely associated with SNPs in UCP2, including rs660339 (Ala55Val), rs659366 (-866G/A), and rs591758." (PMID 29849618, 2018). "Certainly we have previously highlighted a role for UCP2 in telomere regulation and currently in this review we relate UCP2 to obesity regulation." (PMID 28859657, 2017). "Uncoupling proteins 2 (UCP2) plays an important role in energy regulation, previous studies suggested that UCP2 is an excellent candidate gene for human obesity and growth-related traits in cattle and chicks." (PMID 26755944, 2016).
Obesity (continued). "Consistent with the important functions concerning energy balance and body metabolism, the UCP2 is an excellent candidate gene for obesity-related phenotypes in human." (PMID 26755944, 2016). "The early stage of heart failure in obesity is characterized by an overexpression of UCP2 or UCP3 in response to increased FFA and mitochondrial ROS generation and induced mild uncoupling of oxidative phosphorylation without affecting ATP level." (PMID 27642497, 2016). "The anti-obesity and hypolipidemic effects of AFE + VME were associated with the up-regulation of the mRNA expression of PPAR-γ, UCP-2, and adiponectin and the down-regulation of leptin in high-fat-diet-induced obese mice." (PMID 26474757, 2015). "In many pathophysiological conditions such as NAFLD and obesity, UCP2 levels are elevated, indicating increased oxidative stress." (PMID 26077338, 2015). "Genetic association studies have shown that human UCP2 and UCP3 variants (SNPs and indels) are associated with obesity, insulin resistance, type 2 diabetes mellitus, and metabolic syndrome." (PMID 25495519, 2014). "Enhanced UCP2 gene and/or protein expression has been reported in several animal models of resistance to obesity." (PMID 25118945, 2014). "Based on genetic association studies, UCP2, UCP3, or both are reportedly associated with obesity, insulin resistance, type 2 diabetes mellitus, and metabolic syndrome in humans." (PMID 25495519, 2014). "These are the reasons why the roles played by UCP1-3826A/G, UCP2-866G/A, UCP2 Ala55Val, UCP2 Ins/Del and UCP3-55C/T polymorphisms in obesity risk and BMI changes have been extensively studied, although the results of these associations are still inconclusive." (PMID 24804925, 2014). "Pooled measures for the association between the UCP2–866G/A, Ala55Val and UCP3–55C/T polymorphisms and susceptibility to obesity." (PMID 23560041, 2013). "Variants of UCP2 and UCP3 genes have been reported to be associated with obesity, but the available data on the relationship are inconsistent." (PMID 23560041, 2013). "Early in 2001, just 4 years after the discovery of UCP2, it was reported that UCP2 negatively regulated insulin secretion and was a major link between obesity, β-cell dysfunction, and DM2." (PMID 23841103, 2013). "Inhibition of UCP2-mediated proton leak by Genipin has been found acutely to reverse obesity- and high-glucose-induced β-cell dysfunction in isolated pancreatic islets in vitro and in animals with diet-induced T2DM in vivo." (PMID 22110477, 2012). "We measured Ucp2 expression as this has been proposed to be major factor in obesity, beta cell dysfunction, and type 2 diabetes, negatively regulating insulin secretion." (PMID 22808281, 2012). "It has been reported that UCP2 negatively regulates insulin secretion and is a major link between obesity, β-cell dysfunction, and T2DM." (PMID 22110477, 2012). "UCP2 has been widely studied in the context of obesity, diabetes mellitus and inflammatory responses; an absence of UCP2 potentially promotes ROS accumulation and induces oxidative damages and inflammatory response." (PMID 22849356, 2012). "Taken together, these reports suggest that UCP2 has a role in counteracting diet-induced obesity by enhancing peripheral fatty acid metabolism." (PMID 22533685, 2012). "Genipin inhibits UCP2-mediated proton leak and has been shown to reverse obesity, as well as high glucose-induced beta cell dysfunction in isolated pancreatic islets." (PMID 21935467, 2011). "Above information suggests that Sirt1 is involved in regulation of obesity-associated metabolic diseases through regulating PGC-1α, UCP2 and LXR proteins." (PMID 21549004, 2011). "Consistent with this, inhibition of UCP2 activity by genipin, a natural compound from Gardenia, reversed high glucose- and obesity- induced beta cell function." (PMID 19065272, 2008).
Obesity (continued). "In fact,PPARα expression increases in the liver during fasting and in several models of murine obesity.Chronic treatment of rodents with PPARα agonists such asfenofibrate or Wy 14643 increases hepatic UCP2 mRNAexpression." (PMID 17389766, 2007). "Therefore, UCP2 plays a key role in the connection between obesity and inflammation, influencing cellular metabolism affected by oxidative stress and inflammatory status." (PMID 39062809, 2024). "This suggests that dysregulated insulin signaling could be the predisposing factor leading to the inhibition of the Sirt1-Pgc1a-Ucp2 axis, adipocyte dysfunction, and the eventual development of obesity and insulin resistance with age." (PMID 38891115, 2024). "On the other hand, reduced expression of Pomc and Ucp2 as well as hyperphagia would predict, together with the slight decrease in leptin receptor expression, a positive energy balance and obesity, possibly due to partial leptin resistance." (PMID 36581316, 2023). "Based on its high distribution throughout the body, UCP-2 may have a role in several diseases such as obesity, diabetes, cardiovascular disease, neurodegenerative, and psychological disease." (PMID 36900198, 2023). "Studies have reported that some SNPs in UCP2 are related to obesity and type 2 diabetes." (PMID 35181733, 2022). "To summarize, the study demonstrated that high protein diets based on both pork protein and soybean protein effectively alleviated nutritional obesity in already obese mice, which might regulate hepatic lipid metabolism via the UCP2-AMPK-ACC signaling pathway." (PMID 35563950, 2022). "On the other hand, UCP2 is an uncoupling protein which acts as a carrier of protons present in the inner membrane of mitochondria and contributes to thermogenesis, being a positive factor for the prevention of obesity." (PMID 35237168, 2022). "In this study, LT supplementation increased muscle expression of transcripts related to fatty acid oxidation (CPT1, PGC-1a, Tfam, Nrf1, SIRT1, and UCP2) without obesity-induced muscle loss." (PMID 35678694, 2022). "Ghrelin suppresses insulin secretion by regulating uncoupling protein 2 (UCP2) in panarctic β cells; ghrelin ablation attenuates hyperglycemia of leptin-deficient ob/ob mice without affecting obesity." (PMID 35454071, 2022). "Therefore, the negative regulation of insulin secretion by UCP2 represents a strong link between obesity, β-cell dysfunction, and the development of type 2 diabetes." (PMID 35323702, 2022). "Interestingly, research studies have demonstrated a correlation between polymorphisms within the UCP2 gene and metabolic diseases, particularly T2DM and obesity." (PMID 33957975, 2021). "The carrier protein uncoupling protein-2 (UCP-2) on mitochondria also maintains normal mitochondrial function, thus maintaining NO homeostasis and protecting the endothelial dysfunction in diabetes and obesity." (PMID 34439415, 2021). "In addition to the role of UCP2 as a glucose transporter in skeletal muscle, Ucp2 is also involved in the regulation of energy metabolism and obesity." (PMID 34646848, 2021). "Moreover, expression of Cpt1b and Ucp2 in skeletal muscle is up-regulated in the klf5-knockout heterozygous mouse, which is resistant to high fat-induced obesity and glucose intolerance." (PMID 33639916, 2021). "UCP2 is a protective protein against obesity and type-2 diabetes." (PMID 32560241, 2020). "Also, in relation to garlic biocompounds and its anti-obesity properties, it has been identified that thiacremonone enhanced the mRNA level of uncoupling protein-2 (Ucp-2) in 3T·-L1 cells." (PMID 31795191, 2019). "Similarly, an increased expression of UCP2 mRNA was found in obesity-prone models given a lipid-rich diet relative to obesity-resistant mice." (PMID 29351723, 2018). "First of all, UCP2 might play an important role in the regulation of energy expenditure and it is likely to contribute itself to obesity and type 2 diabetes mellitus (T2DM)." (PMID 29163755, 2017).